AFP (alpha fetoprotein)
Diseases named in the same sentence as AFP in open-access papers (continued):
Sharing a sentence is not in itself a finding about the gene and the disease.
tumor (continued). "Univariate Cox regression analysis showed that ALT, GGT, AFP, tumor size, tumor encapsulation, macroscopic tumor thrombus, microvascular invasion (MVI), lymphatic metastasis, differentiation grade, BCLC stage and PGAM1 expression were significantly correlated with the survival of HCC patients." (PMID 37705495, 2023). "The median alpha-fetoprotein (AFP) level was 240.3 ng/mL, and the mean tumor size was 8.2 cm." (PMID 37686699, 2023). "However, it was found that the rs10204525 TC genotype in HCC patients was associated with the AFP level and rs36084323 CT genotypes were related to the HCC tumor TNM stage." (PMID 37131179, 2023). "At present, there are many predictive models established in different medical centers based on risk factors related to early recurrence (such as male, large Tumor diameter, high serum AFP, vascular invasion, low tumor differentiation, etc.)and imaging features." (PMID 37519805, 2023). "the further multivariate regression analysis showed that T stage (P<0.001), N stage (P<0.01), M stage (P<0.001), AFP (P<0.01), tumor size (P<0.01), surgery (P<0.001), and chemotherapy (P<0.001) were independent prognostic factors for OS, which were included in the nomogram." (PMID 36798659, 2023). "After univariate analysis, variables with P < 0.1 of serum AFP level, neutrophil-to-lymphocyte ratio, tumor number, size of the largest tumor, tumor differentiation, macrovascular invasion, Child-Pugh class, and tumor micronecrosis were included in the multivariate Cox regression model." (PMID 36698095, 2023). "Univariate and multivariate Cox regression analyses were performed on the training cohort to evaluate each prognostic factor, T stage, N stage, M stage, AFP, race, grade, tumor size, surgery, and chemotherapy were significantly (P<0.05) identified in univariate analysis in the training cohort." (PMID 36798659, 2023). "AFP immunization significantly delayed HCC tumor formation (P < 0.0001)." (PMID 37040183, 2023). "The few remaining tumor nodules in the livers of the AFP immunization with the anti–PD-L1 combination group may be due to the highly suppressive tumor microenvironment of HCC." (PMID 37040183, 2023). "Similarly, significant difference was seen in five subgroups, including Child–Pugh, AFP, tumor diameter, tumor metastasis, BCLC stage." (PMID 37153113, 2023). "Therefore, the serum AFP level plays a significant role in the identification of the tumor grade and prediction of prognosis." (PMID 37519810, 2023). "Furthermore, the FBXO43 expression was significantly higher in HCC tissues with advanced T stage, late tumor grade, and higher serum alpha fetoprotein (AFP) level." (PMID 36765911, 2023). "AFP promotes tumor growth and recurrence via immunosuppression and tumor vascularization." (PMID 37007138, 2023). "In addition, FNDC4 was negatively correlated with AFP, a tumor marker of HCC, and other cancer-related genes such as AHSA1, GDF1, GPC3 and MDK." (PMID 38021165, 2023). "Tumor markers: gastric protease I, gastric protease II, alpha-fetoprotein (AFP), carbohydrate antigen, cytokeratin 19 fragment, gastrin-releasing peptide precursor, total prostate-specific antigen, free prostate-specific antigen, carcinoembryonic antigen, neuron-specific enolase." (PMID 38115262, 2023). "In Model A, for all patients aged under 65 years, combination treatment (HR = 0.08, 95% CI: 0.02–0.35; p = 0.001), preoperative AFP > 400 ng/mL (HR = 5.21, 95% CI: 1.13–23.99; p = 0.034), and a tumor size ≥ 3 cm (HR = 6.81, 95% CI: 1.35–34.25; p = 0.020) were prognostic predictors of PFS." (PMID 36902673, 2023). "In addition, patients with PS1 tended to have higher levels of aspartate aminotransferase (AST), white blood cells (WBC), platelets (PLT) and AFP as well as larger tumor sizes than those with PS0 (all P<0.05)." (PMID 37434986, 2023). "They believed that AFP levels are correlated with the levels of tumor differentiation." (PMID 36816961, 2023).
tumor (continued). "Furthermore, TRIM6 exhibited a better prognostic predictive role in combination with other conventional prognostic factors such as tumor stage, differentiation grade, serum AFP level, etc.." (PMID 38813007, 2023). "Through the neutral network analysis, we could conclude that the level of AFP is the most important risk factor for MVI-positive patients and the age is the most important risk factor for early-stage HCC with a single tumor." (PMID 37118720, 2023). "Furthermore, KIAA1429 is significantly upregulated in LIHC tissues and correlates with tumor volume, serum AFP levels, microvascular invasion, and TNM stage." (PMID 37606975, 2023). "Further refinement of prognostic assessments and treatment decisions may benefit from the inclusion of tumor biological marker alpha-fetoprotein (AFP) and systemic inflammation indicator C-reactive protein (CRP)." (PMID 38053048, 2023). "The AIFs include one of the following: AFP-3BC, rAFP3D or r3dAFP, which may transport drugs and be subject to endocytosis by tumor cells with high AFPR expression." (PMID 36768863, 2023). "However, in a real-world situation, the reduction of tumor size cannot exceed 100%, which means that patients with positive AFP both before initiation of systemic therapy and surgery (i.e., AFP response = 0) are more unlikely to achieve a pCR." (PMID 37158833, 2023). "Furthermore, the nomogram integrating AST/ALT ratio, AFP, tumor number, and BCLC had improved predictive ability compared with the BCLC staging classification alone." (PMID 36944920, 2023). "The optimal cut-off values of tumor markers to assign the patients into the two groups based on the greatest difference in the RFS were 20 ng/mL for AFP (p = 0.009), 10% for AFP-L3 (p = 0.04), and 40 mAU/mL for DCP (p = 0.076) when the minimum p-value approach was used." (PMID 37190248, 2023). "Multivariate Cox regression analyses revealed that covariates significantly associated with PFS included ≥4 (vs. <4) tumors (adjusted HR, 2.34; p = 0.001), tumor size >10 cm (vs. ≤10 cm) (adjusted HR, 1.75; p < 0.001), and AFP concentration ≥400 ng/mL (vs. <400 ng/mL) (adjusted HR, 1.61; p = 0.001)." (PMID 37346065, 2023). "A correlation of FDG uptake with the level of alpha fetoprotein (AFP), a well-known protein tumour marker of HCC, was indicated and thought to occur because of increased tumour growth and metabolic activity causing increased AFP production and increased glucose uptake." (PMID 37046636, 2023). "AFP needs to be combined with imaging or other tumor markers for HCC screening." (PMID 37091138, 2023). "The PROSASH and PROSASH-II model, which consisted of serum albumin, bilirubin, AFP, macrovascular invasion, extrahepatic spread, and largest tumor size, could predict the survival of patients with HCC treated with sorafenib." (PMID 36910622, 2023). "Interestingly, we observed significant differential expression in HCC patients for CCM2, PGRMC1, and nPRs, along with AFP, demonstrating the importance of the CmPn network in influencing tumor recurrence." (PMID 36980321, 2023). "Researchers have compiled an extensive list of factors that are correlated with HCC recurrence, including tumor size, satellite tumor, capsular integrity, proximity to large vessels, vascular invasion, partial necrosis, AFP level, platelet count, antiviral treatment, and viral etiology." (PMID 37760434, 2023). "However, several factors have been associated with increased Ki-67 expression, including larger tumor size, higher serum alpha-fetoprotein levels, and the presence of vascular invasion." (PMID 37711208, 2023). "AFP levels are the most commonly used tumour marker for HCC." (PMID 37533945, 2023). "Moreover, a high expression of RPS24 is associated with various clinical parameters of the patients, such as AFP and the tumor size, and a poorer prognosis." (PMID 36614249, 2023).
tumor (continued). "In the absence of a standard treatment, clinicians often determine the dominant phenotype of tumor on the basis of radiologic characteristics and the presence of tumor markers, such as AFP or carbohydrate antigen 19-9 (CA 19-9), and recommend standard of care treatment for either HCC or CC." (PMID 36765942, 2023). "Age, sex, bridging before PET/CT and Child stage did not influence cumulative 10-year recurrence rates statistically significant but Milan, “up-to-seven” grade, microvascular invasion, AFP-level, number of lesions, size of lesion, pT-category, Tumor to liver SUV ratio did." (PMID 35451699, 2023). "However, after two cycles of standard chemotherapy, in the setting of decreasing AFP tumor markers, he had progression, and despite a change in systemic therapy, he died of disease." (PMID 36805676, 2023). "Similarly, in the present study, patients with PS1 had significantly higher levels of AST, WBC, PLT, AFP as well as larger tumor sizes than those with PS0 (P<0.05)." (PMID 37434986, 2023). "In addition to its role as a tumor marker, AFP is also used as a maternal serum marker to detect neuronal birth defects as part of a panel with other markers." (PMID 37370914, 2023). "The serum tumor markers AFP, CEA, CA19-9 and CA125 of patients were detected before treatment." (PMID 36803802, 2023). "Furthermore, multivariate Cox analysis revealed that factors, including tumor (T) stage, patient age, tumor grade, serum AFP level, and chemotherapy, also affected patient survival." (PMID 37106014, 2023). "A higher serum AFP level often indicates that the tumor is more aggressive." (PMID 37519810, 2023). "Therefore, lnc-MyD88 and AFP can also be used as effective tumor markers to distinguish HCC from LC, and the AUC value of lnc-MyD88 suggested that lnc-MyD88 had better diagnostic efficiency than AFP in the process of distinguishing HCC from LC." (PMID 36793272, 2023). "Tumor markers, AFP, and GGT confirming the HCC development in rats were evaluated." (PMID 37835585, 2023). "All of the baseline characteristics were well balanced between the two groups including age, gender, BCLC stage, Child-Pugh class, albumin–bilirubin (ALBI) grade, PS score, tumor number, largest size, AFP level, portal vein tumor thrombus (PVTT), and extrahepatic spread." (PMID 38074645, 2023). "Two isoforms of AFP have been described: native AFP (nAFP) and tumor AFP (tAFP)." (PMID 37759769, 2023). "In addition to the CEUS indexes, the maximum tumor diameter and serum AFP level, which are two commonly used indexes, were also included in the final model to ensure the clinical usefulness of the model." (PMID 37519810, 2023). "Not only does eligibility criteria consider size and number, but it also considers tumor biology (including tumor markers such as alpha-fetoprotein (AFP) levels), transplant benefit (i.e., the survival on the waitlist and after LT), and the availability of donor organs." (PMID 38001597, 2023). "Secreted by approximately 70% of patients with HCC, AFP is a well‐recognized tumor marker." (PMID 35698292, 2023). "AFP obviously is a good marker for chemotherapy response and thus reduction of tumor mass, and therefore a high value at the time of pLTx and a lower decrease during therapy could be correlated to the risk of tumor recurrence and thus survival." (PMID 36832331, 2023). "However, there was a significant difference in BCLC stage, Child–Pugh class, serum alpha-fetoprotein (AFP) level, tumor size, portal vein invasion, metastasis, and previous treatments between the two groups." (PMID 37686509, 2023). "The clinical features were as follows: PVTT, tumor number, and AFP." (PMID 37700255, 2023). "Additionally, one moved from purely morphometric criteria to criteria combining morphology and biology, including the French AFP model (combining AFP, tumor size, and number) and the total tumor volume (≤115 cm3)/alpha fetoprotein (≤400 ng/mL) score." (PMID 37760542, 2023).
tumor (continued). "Tumor numbers > 3 (HR = 1.69, 95% CI = 1.21–2.37), AFP ≥ 400 ng/ml (HR = 1.52, 95% CI = 1.10–2.10), PLT < 100 × 10^9(HR = 1.7495% CI = 1.11–2.73), ALP > 150U/L (HR = 1.65, 95% CI = 1.15–2.37) and prior surgery (HR = 0.63, 95% CI = 0.43–0.93) were independent prognostic factors." (PMID 37287040, 2023). "The AFP model focuses on the patient's postoperative tumor recurrence." (PMID 36967432, 2023). "However, the main issue in HCC immunotherapy is the heterogeneity of tumor cells in the expression of the AFP gene and the presence of AFP antigens on the surface of hepatocytes." (PMID 36768863, 2023). "Meanwhile, patients in the UEBMI group were diagnosed more recently (p = 0.013) and had lower levels of ALBI grade (p < 0.001), lower levels of AFP (p = 0.009), smaller tumor size (p < 0.001), earlier tumor stage (p = 0.026), and lower rates of MVI (p = 0.030) and PVTT (p = 0.002)." (PMID 37455560, 2023). "- Tumor stage in relation to tumor site and tumor markers (AFP, Beta- HCG)." (PMID 37182921, 2023). "After grouping according to whether or not to receive treatment, using PSM for age, sex, race, marital status, AFP, tumor size, N stage, and M stage for 1:1 proximity matching, all variables in the two matched groups were not significantly different after PSM." (PMID 37409255, 2023). "Notably, CENPB protein showed prognostic value in patients with stage I/II, AFP levels below 400 ng/ml, and tumor size less than 5 cm." (PMID 37925172, 2023). "To elucidate the correlation between TRscore and clinical features, we analyzed the differences in the distribution of survival status, TNM stage, AFP value, tumor size, and TACE reactivity of the HCC-TACE cohort within the GSE14520 cohort under different TRscores." (PMID 37208604, 2023). "The proportion of patients with poor tumor differentiation and pathological T-stage 3 or 4 was highest in the TBS > 7.9/AFP ≥ 400 ng/mL group, indicating a high tumor burden, and a previous study reported that AFP elevation was correlated with vascular invasion and poor tumor differentiation." (PMID 36831544, 2023). "However, in those cohorts, the median tumor number was only 2; however, in our cohort, nearly half of the patients in the total population and the AFP score 2 group had more than 10 tumors." (PMID 36967432, 2023). "While radiomic features can provide information about the tumor’s radiologic properties, clinical factors such as serum AFP level (implying the overall tumor burden) and higher radiation dose (tumor cells are better eradicated) can provide information about the patient’s overall disease status." (PMID 38001665, 2023). "AFP, as a serological tumor marker for HCC, has been widely used in clinical work." (PMID 37920165, 2023). "AFP was commonly the tumor biomarker that was expressed more highly in tumors (p = 0.038)." (PMID 35455635, 2022). "The R2 subclass has high AFP levels and is the most aggressive tumor among the three subclasses." (PMID 36309506, 2022). "The eligibility criteria can consider many factors besides the tumor size and numbers, such as tumor biology (including alpha-fetoprotein (AFP) concentration), but tumor size is usually the obstacle for HCC patients along with the availability of donor organs and the composition of the waitlist." (PMID 35158918, 2022). "HCC patients with lower GHR hepatic expression exhibited significantly higher frequency of patients with AFP> 100 ng/ml (76.5% vs. 23.5%; p = 0.048); tumor size >5cm (82% vs. 18%; p = 0.02); vascular invasion (85.5% vs. 14.5%; p = 0.002), and advanced TNM stage (80.6% vs. 19.4%; p = 0.01)." (PMID 36374927, 2022). "Preoperative characteristics such as AFP level, tumor volume and number of tumors were included." (PMID 35859667, 2022). "Tumor markers such as AFP and PIVKAII were measured at that time." (PMID 36057621, 2022). "AFP is most commonly used in combination with tumor morphology." (PMID 35002508, 2022).
tumor (continued). "Combined with traditional survival analysis, the final results showed that PVTT invasion, tumor number, AFP, TBIL, and treatment mode were continually the most significant prognostic factors affecting patient survival, consistent with previously reported research." (PMID 36249011, 2022). "Additionally, AFP has been selected as a surrogate marker of tumor biology and integrated into almost all criteria reported in the past decade, including the Hangzhou criteria, the French AFP model, the TTV + FP model, and the Metroticket 2.0 model." (PMID 35053580, 2022). "Besides, bioinformatic analyses indicated that low RCL1 expression was the risk factor of poor survival prognosis and tumor progression, including: advanced TNM classification, high AFP level, vascular invasion in many HCC cohorts." (PMID 35264160, 2022). "We also found that HCC tumors with high CD26 expression showed higher alpha-fetoprotein levels, more advanced tumor stages, poorer histologic differentiation, higher tumor cell infiltration into the tumor capsule, and greater cell proliferation than those with lower CD26 expression." (PMID 35053615, 2022). "Additionally, tumor stage (IV vs I stage, HR: 4.92, 95% CI 1.62–14.97), AFP (<20 vs ≥20, HR: 0.53, 95% CI 0.33–0.85), and CEA (<5 vs ≥5, HR: 0.53, 95% CI 0.33–0.88) were found to be independent prognostic factors for DFS in the multivariate analysis." (PMID 35277188, 2022). "To determine whether Ola reduces the targets of the ph-S675-β-catenin-CEGRs/ALCDs pathway in PDXs, we examined the GPC3 and AFP levels in the tumor tissues of PDXs (n = 6) from three HBL patients treated with vehicle (control) or with Ola." (PMID 36551548, 2022). "In the multivariate analysis, DFS was associated with MELK (HR 2.251; 95% CI 1.274–3.977; p = 0.005), tumor stage (T1 and T2 vs. T3 and T4, HR 2.416; 95% CI 1.398–4.175; p = 0.002), tumor status (tumor-free vs. with tumor, HR 6.558; 95% CI 4.006–10.738; p < 0.001), and AFP (AFP ≤ 200 VS." (PMID 35511171, 2022). "The results showed that an AFP level greater than 400 ng/mL (p = 0.011), tumor size greater than 5 cm (p = 0.004), late-stage HCC (p = 0.007), HCC with vascular invasion (p = 0.001), HCC with metastasis (p = 0.024) and high expression of CD133 (p = 0.001) were associated with decreased OS time." (PMID 35208536, 2022). "Using negative enrichment with CD45- and iFISH®, CTCs were detected in 26 (52%) patients and CTCs count positively correlated with several other prognostic factors like tumor size (χ2 = 5.77, p = 0.016), AFP level (χ2 = 5.45, p = 0.02) and tumor grade (χ2 = 6.48, p = 0.039)." (PMID 36033451, 2022). "Simultaneously, highly expressed SNRPFP1 was significantly correlated with the clinicopathological features of the patients, such as larger tumor size, higher serum AFP quantity, more frequency of later stages of the tumor, and the severe tumor invasiveness either intrahepatic or vascular." (PMID 36535956, 2022). "Univariable Cox analyses revealed that these inflammation-based prognostic models (FAR, NLR, MLR, PLR, and SII) were significantly related to DFS, as well as age, male sex, HBsAg, AFP, CSPH, ascites, tumor size, BCLC stage, blood loss and transfusion, and major hepatectomy." (PMID 35606690, 2022). "The MVI prediction model, consisting of AFP, tumor diameter, and TNM stage, exhibits superior predictive efficacy and strong clinical practicability for MVI prediction and prognostication, which provides a new therapeutic strategy for the standardized treatment of HCC patients." (PMID 36180867, 2022). "Our newly developed score model, which incorporated, in addition to patient factor sarcopenia, tumor number, tumor size, major venous thrombosis, serum AFP, and albumin into consideration, could effectively predict patient survival after TACE." (PMID 36248997, 2022). "Therefore, the use of AFP needs to be optimized, and future studies are needed to evaluate the efficacy of different tumor markers in HCC surveillance." (PMID 36112645, 2022).